IL6 (interleukin 6)
Diseases named in the same sentence as IL6 in open-access papers (continued):
Sharing a sentence is not in itself a finding about the gene and the disease.
benign prostatic hyperplasia (30 papers, 2003 to 2025). A non-cancerous nodular enlargement of the prostate gland. "The correlation analysis showed a relationship between the amount and intensity of IL-6 expression in benign prostatic hyperplasia tissue cells and the percentage of SCFAs isolated from the stool of patients." (PMID 37847180, 2023). "Significant cytokines that play an important role in the immunological inflammation of prostate hyperplasia include IL-6 and IL-8, found in prostatic fluid." (PMID 38107701, 2023). "It has been confirmed in molecular and immunohistochemical studies that IL-6 in benign prostatic hyperplasia is a factor involved in paracrine and autocrine epithelial cell growth regulatory loop." (PMID 37847180, 2023). "There were elevated levels of interleukin IL-8 and IL-6, as well as an increase in prostate-specific antigen among individuals affected by prostatic hyperplasia." (PMID 38107701, 2023). "IL-6 has multiple, distinct, or even contradictory pathophysiological effects in benign prostatic hyperplasia." (PMID 35464825, 2022). "IL-6 and IL-8 in prostatic fluid are important cytokines that mediate the immune inflammation of prostate hyperplasia." (PMID 35386711, 2022). "In benign prostate hypertrophy, IL-6 was preferentially immunolocated in basal epithelial cells, and gp130 was limited to epithelium and stroma." (PMID 35464825, 2022). "Interleukin-6 (IL-6) produced by PC3 cells activates fibroblasts derived from patients with benign prostatic hyperplasia (BPH)." (PMID 35222290, 2022). "Expression of genes encoding IDO, IL-6, IFN-γ, TNF-α, and their receptors was investigated in tumor tissues of PCa patients undergoing radical prostatectomy, in comparison with benign prostatic hyperplasia (BPH) specimens." (PMID 29896191, 2018). "Recent advances in the investigation of cytokines in PCa suggested that IL-6 played an important role in the progression and metastasis of PCa and benign prostatic hyperplasia." (PMID 30333255, 2018). "Therefore, this study conducted a pharmacodynamic evaluation of rape pollen maca chewable tablets on benign prostatic hyperplasia, investigated their impact on gut microbiota, and further explored the IL-6/JAK2/STAT3 signaling pathway in prostatic tissues." (PMID 41472815, 2025). "The involvement of IL-6 in benign prostatic hyperplasia is complex." (PMID 35464825, 2022). "The decreased IL-6 and TNF-α levels in ascites samples after treatment with EH alone and the association of Cph + EH were in accordance with the results of another previously cited in vivo study concerning castrated Sprague Dawley rats with benign prostatic hyperplasia." (PMID 38256751, 2024). "Increased cytokines in benign prostatic hyperplasia (BPH) could induce BPH cells to produce inflammatory mediator, including IL-6, IL-8, and CXCL10 to create a positive feedback loop that can amplify inflammation." (PMID 34659199, 2021). "Serum IL-6 is significantly increased in patients with CRPC when compared to values of healthy controls, patients with benign prostatic hyperplasia (BPH), and localized prostate cancer." (PMID 29562686, 2018). "Through measurement of listed blood and urinary biomarkers of inflammation and oxidative stress such as IL-6 and PGE-M, we investigated the role of systemic inflammation on prostate enlargement and LUTS severity." (PMID 27336586, 2016). "The current study also reports increased levels of IL-6, IL-10, IFN-γ, and IL-12p70 in Brazilian PCa patients, but those were compared to healthy controls, since prostate hyperplasia patients were not included." (PMID 40427694, 2025).
chronic lung disease (30 papers, 2011 to 2025). According to the definitions of the American and British Thoracic Societies, including pulmonary functional tests, X-rays, and CT scans for items such as fibrosis, bronchiectasis, bullae, emphysema, nodular or lymphomatous abnormalities. "Recent research has shown that IL-6 is actively involved in various inflammatory processes associated with the pathogenesis of various chronic lung diseases." (PMID 37887075, 2023). "In preterm neonates with funisitis, elevated plasma interleukin-6 (IL-6) level in cord blood is associated with increased incidence of adverse neonatal outcomes such as chronic lung disease, intracranial haemorrhage, and cerebral palsy." (PMID 31183262, 2019). "In the current study, we show that the pro-fibrotic mediator IL-6 is produced by alveolar macrophages in the airways of ADA-deficient mice that develop features of chronic lung disease in response to elevations in adenosine." (PMID 21799929, 2011). "Mechanistically, chronic IL-6/IL-8-mediated neutrophilic airway inflammation drives immunopathology and functional decline in chronic lung diseases." (PMID 40520197, 2025). "On the other hand, circadian clock disruption during chronic lung diseases has essential effect in augmented oxidative stress and increased systemic inflammation, as evidenced by increased interleukin-6, C-reactive protein, and tumor necrosis factor." (PMID 38225649, 2024). "in the airways with lower levels of inflammatory markers (i.e. IL-8, IL-6 and IL-1β) in chronic lung diseases." (PMID 37168857, 2023). "Specifically, in HIV-1 patients increased levels of circulating interleukin-6(IL-6), Tumour Necrosis Factor-α (TNF-α), interleukin-1 beta (IL-1β) and C-reactive protein have been associated with chronic lung disease." (PMID 32059509, 2020). "In conclusion, our studies demonstrate that IL-6 is an important mediator of inflammation and remodeling in a chronic lung disease model driven by adenosine." (PMID 21799929, 2011). "Previous studies have demonstrated that engagement of the A2BR can promote the release of IL-6 from alveolar macrophages isolated from the lungs of patients with chronic lung disease." (PMID 21799929, 2011). "Collectively, these findings support the model that elevations in adenosine promote IL-6 production from alveolar macrophages through engagement of the A2BR in chronic lung disease." (PMID 21799929, 2011). "However, notable exceptions included a higher prevalence of chronic lung disease in the conventional group compared to the pt-qPCR group (58.0% vs. 20.4%, P < 0.001) and a lower median IL-6 level in the conventional group (133.22 vs. 171.28, P < 0.001)." (PMID 40989843, 2025). "IL-6 is secreted by immune cells and lung endothelial and epithelial cells in response to environmental insults, and via its pleiotropic effects modulates pathogenesis, progression, and severity of various chronic lung diseases." (PMID 33260937, 2020). "Based on these observations, we hypothesized that IL-6 signaling contributes to tissue destruction and remodeling in a model of chronic lung disease where adenosine levels are elevated." (PMID 21799929, 2011). "Collectively, these findings support a pro-fibrotic role for IL-6 in chronic lung disease." (PMID 21799929, 2011). "IL-6 mediated activation of STAT-3 has been implicated in several diseases; however, little is known about the ability of adenosine to activate this pathway in the context of chronic lung disease." (PMID 21799929, 2011). "The ability of adenosine to promote the production of IL-6 together with the pro-fibrotic features of this cytokine led us to hypothesize that this pathway contributes to features of chronic lung disease in environments where adenosine levels are elevated." (PMID 21799929, 2011).
chronic lung disease (continued). "IL-6 is a proinflammatory mediator that can induce lung lesions, aggravate long-term ventilation-induced barotrauma, and accelerate pulmonary inflammatory progression in the premature population, thus promoting pulmonary remodeling and the development of chronic lung disease." (PMID 35463904, 2022). "Furthermore, these findings suggest that IL-6 neutralizing antibodies might be useful in the treatment of chronic lung diseases such as COPD and IPF." (PMID 21799929, 2011). "Adenosine and IL-6 are also elevated in models and humans with chronic lung disease and we speculate that adenosine elevations in chronic environments serve to elevate IL-6 levels that in turn activate inflammatory cascades and promote remodeling processes such as fibrosis and air-space destruction." (PMID 21799929, 2011). "There were 10 variables confounded by both age and male, including diastolic pressure, chronic lung diseases, WBC, IL2R, IL6, ESR, GGT, CURB 65 score, coagulopathy, and DIC." (PMID 34025688, 2021). "Finally, chronic lung disease in the setting of SJIA and MAS has been increasingly recognized in the past decade, in parallel with widespread use of anti-cytokine (IL-1 and IL-6) biologics." (PMID 36964620, 2023). "Furthermore, published studies have suggested that the release of inflammatory cytokines involving IL-1β, IL-6, and TNF-α participated in activating p38 MAPK and JNK signaling pathways in chronic lung diseases." (PMID 35754478, 2022). "In this study AA induced lower levels of IL-6 and CXCL-8 in COPD versus non-COPD pulmonary fibroblasts, suggesting that in COPD meals rich in ω-6 PUFAs are not as potent in the induction of inflammatory responses compared to other chronic lung diseases." (PMID 30390648, 2018).
hepatitis C (30 papers, 2012 to 2025). "In hepatitis C, carriers of the GG genotype had higher levels of IL-6 (p = 0.0286), which were associated with A2–A3 inflammatory activity (p = 0.0097)." (PMID 35336914, 2022). "Hepatitis C is an inflammatory disease associated with elevated expression levels of IL-6 and TNF-α (tumor necrosis factor-α)." (PMID 35887291, 2022). "In vivo studies in mice and hepatitis C patients receiving recombinant pegylated IFN-α injections show that type 1 IFN enhances production of IL-6." (PMID 40845053, 2025). "For example, in patients with hepatitis C who were depressed after receiving interferon-alpha, increased spinal fluid IL-6 and monocyte chemotactic protein 1 levels were noted." (PMID 36711294, 2023). "High levels of IL-6 are associated with HCV infection and, especially, with the most severe forms of hepatitis C." (PMID 35336914, 2022). "For instance, in hepatitis C virus infection, hepatic inflammation increases circulating levels of interleukin 1, tumour necrosis factor alpha and interleukin 6, which all can stimulate IR." (PMID 31470414, 2019). "For example, blocking TIM-3 followed by TLR agonist treatment resulted in the expression of IL-12, interleukin-10 (IL-10), and interleukin-6 (IL-6) in hepatitis C monocytes, and this strategy may be applicable to cancer." (PMID 32087708, 2020). "However, the levels of CRP and IL6 reported in previous studies with less stringent exclusion criteria were much higher and the proportion of participants with known co-morbidities such as hepatitis C was about 20%." (PMID 25888119, 2015). "Hepatitis C virus infection may result in lower production of type 1cytokines including IL-6." (PMID 22768976, 2012). "In patients with chronic hepatitis B and hepatitis C, serum lipid levels have been reported to be correlated with specific cytokines that may have antiviral activity, including tumor necrosis factor-alpha and interleukin-6." (PMID 23193392, 2012). "In multivariate analysis, SHD deficiency correlated significantly with increased IL-6, high serum CTX levels, lower mean daily exposure to the sun, current or past smoking, hepatitis C, and functional status (falls), but not with the time spent on the current HAART (by specific drug or overall)." (PMID 23295013, 2013).
hyperthyroidism (30 papers, 2007 to 2025). Overactivity of the thyroid gland resulting in overproduction of thyroid hormone and increased metabolic rate. "Increased interleukin-6 (IL-6) has been linked to thyrotoxicosis, as shown in a retrospective study where serum IL-6 values were higher in patients with hyperthyroidism compared to those with normal thyroid function." (PMID 36016309, 2022). "For example, genetic variants of TNF-α, IL-1, IL-6, and IL-10 have been reported to increase the risk of hyperthyroidism." (PMID 34567510, 2021). "A meta-analysis demonstrates that TNF-α at 308 G/A and IL-6 at 174 G/C polymorphisms exhibit increased hyperthyroidism risk in Caucasians." (PMID 34567510, 2021). "We report here that TSH and the pathogenic anti-TSHR antibodies that drive hyperthyroidism in GD induce IL-6 expression in fibrocytes and orbital fibroblasts." (PMID 24086448, 2013). "However, Asians show different genetic polymorphisms for hyperthyroidism risk: IL-1α at 889 C/T, IL-1β at 511 C/T, IL-6 at 174 G/C, IL-6 at 572 G/C, and IL-10 at 1,082 A/G polymorphisms." (PMID 34567510, 2021). "Taken together, our data suggest that excess iodine exacerbates hyperthyroidism by increasing IL-6 levels." (PMID 40895623, 2025). "Specifically, patients with hyperthyroidism often exhibit a systemic inflammatory state, characterized by elevated levels of pro-inflammatory cytokines such as interleukin-6 (IL-6) and tumor necrosis factor-α (TNF-α)." (PMID 41357074, 2025). "The serum IL-6 level was higher in clinical hypo- and hyperthyroidism patients coexisting with T2DM, compared with other disease groups (p < 0.001, p < 0.0001)." (PMID 36830883, 2023). "The level of the pro-inflammatory markers (TNF-α, IL-1, IL-4, IL-6, and IL-10) in the hyperthyroidism group of rats was much higher than that of the healthy animals, whereas the level of the apoptotic marker (CD4+) was noticeably lower." (PMID 37020549, 2023). "The corresponding mutated genes set that has common effects on hyperthyroidism in children included IGF1, CACNA1S, MYH7, IL6, TTN, CACNB2, LAMA2, and DMD." (PMID 37876543, 2023). "The results showed that compared with those in the control group, the mRNA expression levels of Tnf-α, Il-1β, and Il-6 in the hyperthyroidism group were significantly increased compared with those in the controls." (PMID 36139036, 2022). "Ultimately, the present research aimed to examine the association of IL-6 with OPG and RANKL in patients with hyperthyroidism." (PMID 36161625, 2022). "Our study showed that hyperthyroidism was associated with an elevation in serum OPG and IL-6 levels while a decrease in serum RANKL in relation to the excess in thyroid hormones." (PMID 36161625, 2022). "Specifically, Prunellae Spica, Moutan Cortex, and Rehmanniae Radix were identified as collectively target IL6 in the treatment of hyperthyroidism, illustrating the multi-component and multi-target mechanisms underlying traditional Chinese medicine interventions." (PMID 41155084, 2025). "Specifically, elevated levels of the pro-inflammatory cytokine IL-6 may promote B-cell differentiation and the production of thyroid-stimulating hormone receptor antibodies (TRAb), thereby exacerbating hyperthyroidism." (PMID 41355999, 2025). "In hyperthyroidism, subcutaneous adipose tissue releases interleukin 6 (IL-6) and tumor necrosis factor-alpha (TNF-α), which could then act as an endocrine mediator of IR in lipolysis." (PMID 39175570, 2024). "It was reported that NF-κB is activated by hyperthyroidism, which is crucial for controlling the genetic transcription and encoding of inflammatory cytokines including IL-10, IL-4, TNF-α, and IL-6 that, in turn, promote NO, lipid peroxidation and free radical generation." (PMID 37020549, 2023). "We concluded that increases in serum OPG and IL-6 levels accompanied hyperthyroidism." (PMID 36161625, 2022).
hyperthyroidism (continued). "Our results suggested that OPG, RANKL, and IL-6 might be involved in the cross-talking among immunity, thyroid function, and bone metabolism in the case of hyperthyroidism." (PMID 36161625, 2022). "IL-6 may induce either the onset or relapse of hyperthyroidism in GD as reported in two case reports, and GD relapse cases have been described in convalescent patients, too." (PMID 33765288, 2021). "A strict relationship between the severity of systemic inflammation, particularly IL-6, and hyperthyroidism was found, and COVID-19 patients with hyperthyroidism and thyrotoxicosis displayed poor prognosis and more extended hospital stay compared to euthyroid patients." (PMID 33765288, 2021). "Also opposite to the results obtained in TRs KO mice, hyperthyroidism resulted in increased hepatic levels of IL-6 and SOCS3 transcripts in response to 5 mg/kg LPS or 20 mg/kg LPS, while TNFα and IL-10 mRNAs remained unchanged." (PMID 27484112, 2016). "Finally, OPG, RANKL, and IL-6 might be involved in the cross-talking among immunity, thyroid function, and bone metabolism in the case of hyperthyroidism." (PMID 36161625, 2022). "In terms of outcome, TNF-α, IL-6, IL-10, IFN-γ, and relapse rate were added in this study to comprehensively evaluate the efficacy of the PVL preparations in intervening in hyperthyroidism." (PMID 40083379, 2025). "Once infected with H. pylori, cytokines such as interleukin (IL)-4, IL-5, and IL-6 are activated, initiating a cascade of humoral immune responses that may modify the expression of adhesion molecules on the gastric mucosa, thereby contributing to the hyperthyroidism observed in GD." (PMID 39963276, 2025). "Based on these contradictory results, the present study aimed to investigate the relationship between IL-6, which is a part of immunity, and OPG and RANKL, which are involved in bone metabolism in patients with hyperthyroidism." (PMID 36161625, 2022). "The highest concentrations of IL-6, IL-12, and IL-18 were observed in the subjects with GD, which might suggest a strong stimulation of the immune response; however, the difference in proinflammatory cytokine levels between the patients with hyperthyroidism due to GD and TNG was insignificant." (PMID 24367378, 2013). "With regard to Graves' disease, elevated IL-6 levels have been described in TAO and hyperthyroidism." (PMID 21209948, 2010). "Bayesian network analysis in the hyperthyroidism group revealed complex interrelationships among FT3, FT4, TSH, IL-15, leptin, IL-6, and TNF-α, with TSH significant regulating inflammatory responses and SMI potentially influencing pre- and post-exercise glucose levels." (PMID 41355999, 2025). "The findings showed that hesperidin significantly modulated hyperthyroidism deteriorations, this was evidenced by a remarkable decline in serum T4, FT4, T3, FT3, TNF-α, IL1β-, IL4-, IL-6, and IL-10 levels, with a minor increase in TSH and significant raise in CD4+ level." (PMID 37020549, 2023). "Interestingly, treatment of hyperthyroidism-modeled group with hesperidin therapy dramatically decreased blood levels of TNF-α, IL-1, IL-4, IL-6, and IL-10 while sharply increasing CD4+ level close to healthy controls." (PMID 37020549, 2023). "Because TSIs rather than TSH activate TSHR in GD and drive hyperthyroidism, these mAbs (M22, 2 μg/mL) were tested and found to induce IL-6 after 16 h by 22- and 46–fold in fibroblasts and fibrocytes, respectively (both p<0.001)." (PMID 24086448, 2013). "Increased plasmatic concentrations of IL-6, IL-12, IL-18, fibrinogen, VCAM-1, and von Willebrand factor, reported in patients with hyperthyroidism and COVID-19 infection, may also contribute to the hypercoagulability state and increase the risk of thromboembolic events." (PMID 36016309, 2022).
hyperthyroidism (continued). "It is interesting to emphasize, that effective treatment of the thyroid condition related to TAO, i.e. hyperthyroidism, does not lead to a normalization of IL-6 levels in these patients which suggests that IL-6 might not originate from the thyroid." (PMID 17319961, 2007). "However, in evaluating the effects of PVL preparations on relapse rate, IL-6, and IFN-γ, the results of this study have not been able to demonstrate a significant reduction in relapse rate, IL-6, and IFN-γ levels in patients with hyperthyroidism." (PMID 40083379, 2025).